CD4 (CD4 molecule)
Diseases named in the same sentence as CD4 in open-access papers (continued):
Sharing a sentence is not in itself a finding about the gene and the disease.
COVID-19 (continued). "Nevertheless, individuals with severe COVID-19 may also present with lymphopenia, characterized by a significant reduction in peripheral CD4+ T-cell and CD8+ T-cell counts." (PMID 33584343, 2021). "It was shown that some vaccines, such as COVID-19 mRNA vaccines, induce broad CD4+T cell responses." (PMID 34959898, 2021). "Elevated inflammatory cytokines, and loss of CD4+ and CD8+ T cells in the deceased COVID-19 patients, may cause strong inflammation, cytokine storms, and eventually more severe tissue damage." (PMID 33664741, 2021). "The CD4+ T cell proportion was negatively associated with the CD8+ T cell proportion in male COVID-19 patients; this correlation was non-significant in females." (PMID 33350432, 2021). "Indeed, all individuals who have recovered from COVID-19 carry virus-specific CD4+ T cells, which is strongly indicative of a crucial role for the immune response in the successful elimination of SARS-CoV-2." (PMID 34573071, 2021). "We observed several folds of increases in the SARS-CoV-2 antigen-reactive T cells over the control T cells, indicating that DCs presenting the SMENP epitopes (CTL + COVID-19) elicited a strong anti-SARS-CoV-2 T-cell response in both CD4 and CD8 T cells (CD107a, IFN-γ, TNF-α, and IL-2)." (PMID 34451952, 2021). "Interestingly, high magnitude of Spike- and remainder of the genome CD4+ T cell responses are present in the patients long after recovery from mild COVID-19." (PMID 33777028, 2021). "Indeed, when considering changes within each data set, M1 macrophages, plasmacytoid dendritic cells, CD14 + monocytes, CD4+ T cells, and total T cells showed change consistently in the same direction across all viral infections including COVID-19." (PMID 33437935, 2021). "Results suggest that an increase in IgG proteins and complement pathway activation may be leading to the downregulation of CD4 T-cell activation in severe COVID-19 patients." (PMID 34899680, 2021). "COVID-19-associated CSS usually had more obvious leukopenia, thrombocytopenia and lymphocytopenia especially CD4+ T and CD8+ T cells, which leading to lowered IFN-γ production, All of these were identified as an independent predictor of more severe and critical COVID-19." (PMID 33522893, 2021). "Taken together, immunosuppressed RTx patients are able to generate SARS-CoV-2 cross reactive T cells, which are comparable to those of healthy blood donors but with a clearly lower frequency of CD4+ T cells reactive to M and N proteins compared to COVID-19 patients." (PMID 34228322, 2021). "Similarly, our in vitro expansion experiments showed that the SARS-CoV-2-specific CD4+ memory T cells of 57.97% and 94.44% of close contacts and COVID-19 patients, respectively, were able to proliferate." (PMID 33741972, 2021). "This inter-individual variability may, in part, account for the heterogeneity in the presence and magnitude of CD4+ T-cell and antibody responses against the Nucleocapsid protein noted in recent COVID-19 studies." (PMID 34349756, 2021). "Due to the observed downregulation of CD86 and upregulation of PD-L1, DC3 and classical monocytes isolated from the blood of COVID-19 patients may be impaired in their ability to stimulate naïve CD4+ T cells." (PMID 34614036, 2021). "People living with HIV (PLWH) have been disproportionately affected by COVID-19 and are at increased risk for severe clinical symptoms and mortality due to SARS-CoV-2 infection, especially among those with lower CD4+ T cell counts or unsuppressed HIV viral replication." (PMID 34960204, 2021). "Both decreased CD4+T [HR:13.659; 95%CI: 3.235–57.671] and CD8+T [HR: 10.883; 95%CI: 3.277–36.145] cell levels were associated with in-hospital death in COVID-19 patients, but only the decrease of CD4+T cell level was an independent predictor of in-hospital death in COVID-19 patients." (PMID 33435865, 2021).
COVID-19 (continued). "Additionally, the decreased numbers of CD4+ T-cells observed in severe COVID-19 can contribute to hyper-inflammation via the impaired regulatory mechanisms of the inflammatory process or via impaired adaptive T- and B- cell responses." (PMID 34512643, 2021). "Besides the discoveries of reported transcriptomic immune profiles of T cells in patients with COVID-19, our scRNA-seq data showed that histone-related genes were highly expressed in the total T cells, CD4+ T, and CD8+ T cells, both in SCPs cases." (PMID 33717140, 2021). "Using flow cytometry, we observed that specific IFNγ+ and triple+CD4+ T cells, the most important subsets in the orchestration of the whole adaptive immune response, were lower in COVID-19-naive older participants than in COVID-19-naive young adults." (PMID 34868051, 2021). "This study demonstrated that lower CD4 counts might waive the clinical symptoms and inflammatory responses in COVID-19, which would advance our understanding of the virus–immune system interaction in clinical settings." (PMID 34646783, 2021). "Moreover, it will be very important to determine if similar characteristics of memory CD4+ T cells exist in the recovery from different outcomes of disease from the asymptomatic to the severe COVID-19." (PMID 33777028, 2021). "They found a similar infiltrate of CD3+ T cells within precapillary and postcapillary vessel walls; among these, CD4+ T cells were revealed as more numerous in the lungs from patients with COVID-19 than in those from patients with influenza, whereas CD8+ T cells were less numerous." (PMID 34769454, 2021). "Notably, studies evaluating the immune profile of moderate/severe COVID-19 patients showed a decline in CD4+ and CD8+ T cell numbers during the acute phase of SARS-CoV-2 infection with evidence of T cell functional exhaustion." (PMID 34858405, 2021). "Similarly, the levels of Treg cells (CD3+CD4+CD25+CD127low+) were significantly lower from admission to day 7 in the ICU COVID-19 patients (p = 0.001 and p < 0.001, respectively)." (PMID 34071149, 2021). "In COVID-19 patients-receiving ongoing immunomodulating/suppressive drugs, close monitoring of blood count changes, liver and kidney toxicity and, parameters such as IgG, IgM and CD4 T-cell numbers are justified." (PMID 33683393, 2021). "Our patients showed in most cases a good immunological condition, so a low CD4 + lymphocyte count did not seem to be associated with an increased risk of COVID-19, while comorbidities were often present." (PMID 32748333, 2021). "Frequency analyses showed Spike cross-reactive T cells as detected by tetramers were present at relatively low frequency in unexposed people and only contributed a small proportion of the overall Spike-specific CD4+ T cells in COVID-19 convalescent individuals." (PMID 34965282, 2021). "Three RCTs reported the effect of CHM on CD4+/CD8+ ratio in COVID-19 patients." (PMID 35127733, 2021). "Moreover, we also show that immunological memory to SARS-CoV-2 is detectable in mild COVID-19 patients up to 5 months (median ~3 months) after recovery both in the CD4+ T cells and B cells." (PMID 33777028, 2021). "CD4+ T and CD8+ T cells specific for SARS-CoV-2 infections recognize peptides associated with the nucleocapsid, spike protein, and membrane proteins (M) of the virus and are present in most COVID-19 patients." (PMID 34440721, 2021). "Moreover, we observed significantly higher frequencies of tp SARS-CoV-2 S C-terminal reactive CD4+ T cells in post COVID-19 Ab+ compared to HC (p = 0.0008)." (PMID 34322120, 2021). "In summary, severe COVID-19 patients’ lungs exhibit an increase in naive and resting CD4 T-cells." (PMID 34899680, 2021). "SARS-CoV-2 spike glycoprotein (S)-reactive CD4+ cells were detected in 83% of patients with COVID-19, as well as in 35% of healthy subjects demonstrating the presence of S-cross-reactive T cells, probably generated during previous infections with endemic coronaviruses." (PMID 33669527, 2021).
COVID-19 (continued). "Moreover, the overall profile of SARS-CoV-2–specific CD4+ T cells differed significantly between patients who survived COVID-19 and patients who died." (PMID 33945513, 2021). "However, the intensities of SARS-CoV-2-specific CD4+ T cell responses induced by two doses of vaccination were still only one-third of the responses that we detected in convalescent individuals after COVID-19." (PMID 35003131, 2021). "Moreover, a previous study showed most of patients who recovered from COVID-19 had S protein-specific CD4+ and CD8+ T cells in the peripheral blood." (PMID 33750975, 2021). "In addition, a significant decrease of PD-L1 levels (p<0.001) was detected in CD4+ T cells stimulated with interferon in COVID-19 patients as compared to healthy donors." (PMID 34163490, 2021). "Moreover, we found detectable immune memory in mild COVID-19 patients several months after recovery in the crucial arms of protective adaptive immunity; CD4+ T cells and B cells, with a minimal contribution from CD8+ T cells." (PMID 33777028, 2021). "A pattern of antigen immunodominance in convalescent COVID-19 donors has been identified with nine viral proteins being responsible for 83% of the total CD4+ T-lymphocyte response, while eight viral proteins account for 81% of the total CD8+ T-lymphocyte response." (PMID 35046961, 2021). "Consistently, another study found that the levels of tumor necrosis factor-α (TNF-α) and IFN-γ in CD4+ T cells of severe COVID-19 patients were lower than those of mild patients, while the levels of granzyme B and perforin in CD8+ T cells of severe patients were higher than those of mild patients." (PMID 33987176, 2021). "This means that patients with severe COVID-19 have markedly lower absolute number of T lymphocytes, CD4+T and CD8+ T cells and, since the lymphocytes play a major role in maintaining the immune homeostasis, the patients with COVID-19 are highly susceptible to fungal co-infections." (PMID 34036149, 2021). "However, in COVID-19 patients, the total number of CD4+ and CD8+ T cells was significantly reduced, and their phenotype exhibited exhaustion markers, which usually lead to the functional impairment of T cells." (PMID 34805136, 2021). "Our data led us to suggest that the T-cell inflammatory states accompanied with defective functions in the CD4+ T cells of SCPs may be the key factors for determining the pathogenesis of and recovery from COVID-19." (PMID 33717140, 2021). "To verify this hypothesis, at first, we incubated in vitro exosomes of COVID-19 patients and HDs with autologous CD4+ T cells and analyzed cell proliferation." (PMID 35111156, 2021). "COVID-19 patients exhibit a reduction in the absolute number of lymphocytes, including CD4+ and CD8+ T lymphocytes, which display markers related to activation or exhaustion/senescence, in addition to altered expression of master regulators and several chemokine receptors." (PMID 34571981, 2021). "The results indicated that depletion of CD4+ T cells may be responsible for the development of severe illness in the subgroup of COVID-19 patients with obesity." (PMID 33746594, 2021). "Moreover, COVID-19 adults had higher levels of immune senescent T and B cells compared to children, and a higher expression of CD4 and CD8 exhausted cells compared to children." (PMID 34659235, 2021). "In support of this possibility, the repRNA vaccine induced robust humoral immune responses in animals with low to moderate peripheral CD4+ T-cell counts of 400-750 cells/μL of blood, but further evaluation of COVID-19 vaccines in a setting of severe CD4 depletion (< 250 cells/μL) is needed." (PMID 34992610, 2021). "Finally, transcriptomic profiling revealed an altered pattern of CD4+ and CD8+ T cell gene expression in patients who recovered from COVID-19 that particularly affected the CD4+ T cell subpopulation, with less dysregulation observed in CD8+ T cells." (PMID 34784300, 2021).
COVID-19 (continued). "For example, neutralizing antibodies, and responses from CD4+ and CD8+ T cells, might be associated with COVID-19 severity, with age being a risk factor." (PMID 33717166, 2021). "Interestingly, scRNA-Seq studies in patients with COVID-19 identified a similar population of CD4+ CTLs alongside cytotoxic Tfh cells; and the abundance of these cytotoxic populations correlated with limited Treg responses and severe disease." (PMID 34403374, 2021). "Indeed, patients with severe COVID-19 harbor a marked decrease in the absolute cell counts of T cells (both CD4 and CD8), B cells, and NK cells." (PMID 34373466, 2021). "Recent studies carried out in Australia, Germany, Sweden, the United Kingdom, and the United States have reported a particularly high frequency of S-specific CD4+ T cell responses among COVID-19 early convalescent patients approximately 1 month PSO7,21,23,24,33–35." (PMID 33563974, 2021). "A COVID-19 vaccination did not cause severe side effects and had no negative impact on CD4+ T cell counts and HIV RNA viral load." (PMID 34960204, 2021). "With a memory and Th1 phenotype, CD4 T cells in COVID-19 could express IFNγ, the signature cytokine of Th1 responses." (PMID 33907514, 2021). "Notably, depletion of IFNγ secreting CD4+ T cells has been reported in hospitalized COVID-19 patients with a trend towards a greater reduction in severe disease." (PMID 34113347, 2021). "Peripheral lymphocyte subset alteration showed an obvious association with the clinical characteristics of COVID-19, our study did not monitor lymphocyte subsets, including CD4+T cells, CD8+T cells and B cells." (PMID 34222268, 2021). "To determine the extent of cellular cross-reactivity to SARS-CoV-2 antigens, we stimulated CD4+ T cells of 60 unexposed healthy donors and 59 COVID-19 convalescents as controls with peptide pools covering all open reading frames (ORFs) of SARS-CoV-2, referred to here as the “SARS-CoV-2 orfeome”." (PMID 34465633, 2021). "However, we observed that severe COVID-19 patients display strongly up-regulated IL-4 production in both CD4+ and CD8+T cells." (PMID 33692788, 2021). "Despite effective ART and normalized CD4 cell counts, a subset of PWH continue to experience immune activation, inflammation, and a procoagulatory state, which may modulate the risk of COVID-19 related morbidity and mortality." (PMID 33095853, 2021). "Although few differences between groups were observed based on immunophenotyping, we observed increases in antigen-specific CD4+ T cell responses to the SARS-CoV-2 S-protein in COVID-19 patients with prolonged symptom duration at the late convalescent time point." (PMID 34143754, 2021). "Moreover, CD8+ Tem cells were significantly increased in patients with severe COVID-19, and CD4+ Tem cells were significantly increased in COVID-19 patients with either mild or severe COVID-19." (PMID 33546489, 2021). "We then calculated a second scoring to investigate whether CD8+ T cell clusters from the BALF of patients with COVID-19 might receive help from CD4+ T cells." (PMID 33622974, 2021). "Thus, immune responses of CD4+T cells were hyper-inflammatory and activated in early phase of COVID-19, and they underwent functional change during recovery process." (PMID 35095832, 2021). "Also in SARS-CoV-2 infected individuals, lymphopenia with drastically reduced CD4+ and CD8+ T cells correlates with COVID-19-associated disease severity and mortality." (PMID 34194438, 2021). "We observed that the number of CD4+ and CD8+ T cells increased during the convalescence period of COVID-19, and the increased number of CD4+ T cells in patients with low baseline CD4+ T cell counts was significantly higher than in those with normal CD4+ T cell counts." (PMID 34149679, 2021). "However, we found a significant reduction in the frequency of M. tuberculosis–specific CD4+ T cells in COVID-19 patients compared with healthy prepandemic participants with LTBI." (PMID 33945513, 2021).
COVID-19 (continued). "Possibly, HU may also in COVID-19 attenuate viral load by decreasing CD4 T cell proliferation and preventing the exhaustion of CD8 T cells." (PMID 34638236, 2021). "Post-COVID-19 monocytes showed “back-to-normal” expression features such as the downregulation of IL-10 and the upregulation of CD4 and HLA-DRA, which was in agreement with the flow cytometry data showing an increase of HLA-DR expression in monocyte surface after recovery." (PMID 34572439, 2021). "It seemed, therefore, that low levels of CD4+ CD38+ cells in COVID-19(+) patients could distinguish these patients from other inflammatory diseases." (PMID 33419040, 2021). "Fibrotic remodeling of the lung might be driven by skewing of adaptive T cell responses toward impaired regulatory T cell (CD4+ Treg) function and increased Th17 differentiation as observed in severely ill COVID-19 patients." (PMID 34267671, 2021). "Regarding the CD4+ T cell compartment, our previous analysis highlighted an overall restoration of the COVID-19-related skewed CD4 polarization at two months post infection, except for some individual cases with a higher prevalence of the Th9- and Th17-type subsets." (PMID 33800807, 2021). "After 20 days of hospitalization, with clinical improvements, all patients had increased CD4 T cells and lymphocytes (p < 0.05), which may have been caused by the antiretroviral therapy for HIV or immune activity in COVID-19." (PMID 34646783, 2021). "Most recent studies demonstrate that COVID-19 patients with higher numbers of CD4+ CD28null, CD8+ CD28null, or CD4+ CD28null and CD8+ CD28null populations (or presented as lower numbers of CD28+ populations in some studies) have higher morbidity and mortality rates." (PMID 34680058, 2021). "Lastly, decreased expression of PD-L1 on CD4+ interferon-stimulated T cells in COVID-19 patients may reflect the induction of a hyperactivation status which causes an excessive immunopathology." (PMID 34163490, 2021). "This may have been the most probable risk factor for PJP development in our cohort, together with CD4+ lymphopenia, which has been largely observed in patients affected by COVID-19, correlating with a poor prognosis, especially in younger patients." (PMID 34769913, 2021). "In severe COVID-19 patients, CD4+ T cells are hyperactivated, but Foxp3 expression is repressed." (PMID 34631206, 2021). "Our work demonstrates differences between sexes in circulating monocyte counts and CD4+ T cell and CD8+ T cell proportions in COVID-19 patients, independent of estrogen levels, are associated with the clinical manifestations in COVID-19 patients with high specificity." (PMID 33350432, 2021). "Results of univariate and multivariate logistic regression in our study indicate, that expression of CD38 on CD8+ cells alone or together with expression of PD-1 on CD4+ cells could be used as a biomarker of survival in hospitalized patients with COVID-19." (PMID 33937096, 2021). "Consequently, unexposed persons have been found to contain CD4+ T cells that recognize the COVID-19 S2 protein, while the infected individuals seem to have CD4+ T cells that do not discriminate between the S1 and S2 protein subunits." (PMID 34681059, 2021). "Previous data on acute and chronic viral infection, including SARS-CoV-1 and MERS-CoV, as well as several studies analyzing SARS-CoV-2 T cell responses during or early after COVID-19, have shown that CD4+ T cells play a central role in cellular immunity to SARS-CoV-2." (PMID 33723016, 2021). "CD4 T cells in both COVID-19 cohorts more frequently expressed PD-1, a marker of T-cell exhaustion." (PMID 33420356, 2021). "Their suspected high rate of asymptomatic infections in children and adults might assume that these S-reactive CD4+ T cells have protective role in COVID-19." (PMID 33937545, 2021).